NQO1 (NAD(P)H quinone dehydrogenase 1)
Diseases named in the same sentence as NQO1 in open-access papers (continued):
Sharing a sentence is not in itself a finding about the gene and the disease.
cancer (continued). "However, normal cells have lower NQO1 and are more β‐lap insensitive than cancer cells (Kung, Lu, & Chau, 2014)." (PMID 31353811, 2019). "Data show that RH1 can be useful to treat cancers in the NQO1-independent way, and targeting of the cancer stem cells might be an effective approach for combating resistance to RH1 therapy." (PMID 31336714, 2019). "The overexpression of NQO1 promotes the progression of cancer burden and makes the cancer cells more resistant to chemotherapeutic drugs such as 5-FU or cisplatin (oxidative stress inducers) making NQO1 as a potential oncotarget to improve the therapeutic efficacy." (PMID 31858276, 2019). "Compounds such as β-lapachone will not be useful, for example, when cancer cells are homozygous for the NQO1*2 isoform, because these types of compounds cannot be bioactivated by the NQO1*2 variant." (PMID 31480790, 2019). "Finally, deoxynyboquinone was originally synthesized while studying the antibiotic nybomycin and it has been reported to have a tenfold superior efficacy compared to that of β-lapachone in killing different cancer cell lines in a NQO1-dependent manner." (PMID 31388334, 2019). "In other example, individuals with a lack of NQO1 due to a genetic polymorphism show an increased susceptibility to certain cancers." (PMID 31886179, 2019). "Similarly, a role of NQO1 in chemotherapeutic resistance has been demonstrated and inhibition of NQO1 has been shown to suppress cancer cell growth and to potentiate cytotoxicity of anticancer agents." (PMID 31384396, 2019). "HO-1, a cytoprotective enzyme, regulates antioxidative and inflammatory responses, and NQO-1 is involved in detoxification, which may inhibit cancer initiation by detoxifying and eliminating carcinogens." (PMID 31072358, 2019). "It is hypothesized that high level of NQO1 expression promotes carcinogenesis and cancer progression while also making cells more resistant to anticancer drugs particularly oxidative stress inducers." (PMID 29914576, 2018). "Although a lower or absent NQO1 activity is correlated with increased susceptibility for development of human cancers, NQO1 is overexpressed in numerous human cancers." (PMID 30595797, 2018). "Therefore, the combination of PARP inhibitors and β-lapachone blocks DNA repair and induces tumor-selective apoptosis in NQO1-overexpressing cancers." (PMID 30631755, 2018). "Our data strongly indicated that bL has an inhibitory effect on cell proliferation in an NQO1-dependent manner, suggesting that certain cancer stem cells expressing NQO1 could be potential therapeutic targets of bL." (PMID 30513573, 2018). "In addition, pancreatic cells have lower NQO1 levels and are more insensitive to dunnione than cancer cells." (PMID 30584237, 2018). "HO-1 and Nqo-1, as the downstream genes of Nrf2, increased after cancer cell CM stimulation." (PMID 30180849, 2018). "Beta-lapachone (β-lap) is a quinone derived from the bark of South American Lapacho tree (Handroanthus impetiginosus) that exerts specific anti-tumour effects by capitalising on the increased concentration of NAD(P)H:quinone oxidoreductase 1 (NQO1) in cancer cells vs. normal cells." (PMID 30318513, 2018). "Instead of driving cancer cell survival pathways that can be inhibited by targeted therapies (e.g. epidermal growth factor receptor, vascular endothelial growth factor receptor), NQO1 activates ARQ 761 to exert cytotoxic effects via oxidative stress." (PMID 30318513, 2018). "The success of the prevalent cancer treatment with cisplatin is also affected by the NQO1 activity." (PMID 28236663, 2017). "On the other hand, the involvement of NQO1*3 in the development of cancer is currently unclear." (PMID 28236663, 2017). "Similarly, the warfarin-like drug Dicoumarol, was sufficient to overcome tamoxifen-resistance in ER(+) cancer cells, by targeting the protective effects of NQO1 on cancer cell mitochondria." (PMID 29253841, 2017).
cancer (continued). "There is also considerable interest in NQO1 as a cancer therapeutic target." (PMID 28748640, 2017). "TSA and β-lap can both trigger NQO1 bioactivation and induce apoptosis of cancer cells." (PMID 27566573, 2016). "The role of NQO1 in cancer varies due to its role in redox biology." (PMID 26822308, 2016). "Here we show a previously undescribed function for NQO1 in stabilizing HIF-1α, a master transcription factor of oxygen homeostasis that has been implicated in the survival, proliferation and malignant progression of cancers." (PMID 27966538, 2016). "Exploitation of NQO1 as a target for cancer therapy typically entails two strategies." (PMID 26822308, 2016). "However, the specific mechanism of how cancer cells sense NQO1-triggered redox conditions and thereafter initiating apoptotic and/or necroptotic cell death remains largely elusive." (PMID 27566573, 2016). "Remarkably, hypoxic accumulation of HIF-1α was further amplified in NQO1 expressing cancer cells that may accelerate the tumour growth." (PMID 27966538, 2016). "Several nitroreductases, including the mammalian NQO1, are upregulated in cancer cells and our finding that CNOB alone has little anticancer effectiveness in mice suggests that these enzyme levels must be ineffectual in activating this prodrug for treatment purposes." (PMID 27457630, 2016). "We previously reported NQO1-dependent, ROS-induced S-nitrosylation and nuclear translocation of GAPDH in various NQO1 cancer cells after β-lap treatment, and reactive nitrogen species-mediated irreversible inhibition of GAPDH has also been previously shown in vitro." (PMID 25590809, 2015). "In addition, the ability of Nqo1 to reduce small molecule quinones has been studied as a basis for cancer chemotherapy." (PMID 26325183, 2015). "Moreover, high NQO1 expression has been observed in many cancers of the liver, thyroid, breast, colon and pancreas." (PMID 25885439, 2015). "Here, we report that NQO1 mediates OGD-induced cancer cell death." (PMID 25586669, 2015). "NQO1 is highly expressed in many types of cancer, including PDA." (PMID 26462257, 2015). "Thus, one can imagine that a competition between the rates of engagement of the anti-oxidant machinery and the production of ROS determines the fate of cancer cells within a tumor following NQO1-bioactivatable drug treatment." (PMID 26462257, 2015). "It should be noted that Keap 1 is an important target for the bioactivity of XN, such as cancer chemo-prevention, hepatic protection, anti-inflammation, because alkylation on Keap1 activates antioxidant enzymes, such as quinine reductase, NQO1, HO-1, via the regulations of Nrf2." (PMID 25574819, 2015). "Strategies for increasing cancer cell cytotoxicity, while maintaining NQO1 specificity, could further enhance efficacy of ß-lap for therapy against PDAs." (PMID 26462257, 2015). "OGG1 knockdown, dicoumarol-treatment or NQO1- cancer cells were spared." (PMID 26602448, 2015). "To date, the association and correlation between NQO1 and Nrf2 expression in cancers of the female reproductive system have not been adequately studied." (PMID 28983331, 2015). "Our results with previous results indicate that NQO1 up-regulation may be an early event in cancer progression." (PMID 28983331, 2015). "Paradoxically, increasing evidence suggests that high expression of NQO1 at the early stages of carcinogenesis may provide cancer cells with a growth advantage." (PMID 25885439, 2015). "It is also important to note that the intrinsic and/or inductive expression of UGT1A in cancer cells may confer resistance to NQO1 targeting substrates." (PMID 25692465, 2015). "In addition, previous results noted more NQO1 overexpression in carcinoma than in normal or precancerous lesions in breast, colon and liver, and the difference reached a significant level." (PMID 28983331, 2015).
cancer (continued). "The high proportion of NQO1 expression suggests that NQO1 may be a significant biomarker and a potential therapeutic target for carcinoma patients." (PMID 28983331, 2015). "Recently, a role of NQO1 in cancer chemotherapy has been demonstrated by several groups." (PMID 24460787, 2014). "This suggests that in NQO1 expressing patients, treatment with a low dose of 17-AAG could still selectively target cancer cells and have minimal effects on normal cells, even though they may express NQO1." (PMID 24886060, 2014). "Since NQO1 greatly enhances the anti-cancer effects of 17-AAG, this could be used as a selective marker for patients that would benefit most from 17-AAG chemotherapy at low doses." (PMID 24886060, 2014). "Since NQO1 is also an antioxidant enzyme, it may protect cancer cells by removing free radicals and making cells more resistant to anticancer agents, particularly to oxidative stress inducers." (PMID 24460787, 2014). "These compounds may also be valuable in increasing β-lapachone cytotoxicity for cancer cells with low NQO1 expression or activity." (PMID 24505400, 2014). "Furthermore, the strongly positive rate of NQO1 protein was higher in cancer cases with high Her2 expression compared to those with low Her2 expression." (PMID 24499631, 2014). "As some CCA patients express high NQO1, targeting the NQO1 by suppressing the activity or expression could be a strategy to overcome drug resistance of cancer and enhancing the efficacy of chemotherapeutic agents." (PMID 24460787, 2014). "Increasing number of evidences suggest that up-regulation of NQO1 at the early process of carcinogenesis may provide cancer cells a growth advantage." (PMID 24460787, 2014). "Oxidoreductase activity plays a role in cancer too, since a recent meta-analysis of 21 studies has shown that polymorphisms in the NAD(P)H quinine oxidoreductase 1 (NQO1) gene are significantly associated with digestive tract cancer risk among Europeans and Asians." (PMID 25003081, 2014). "NQO1 is an emerging and promising therapeutic target in cancer therapy." (PMID 22848731, 2012). "Because NQO1 is abundantly expressed in a variety of cancer tissues, it may be surmised that cancer tissues can be damaged selectively by β-lap." (PMID 21738692, 2011). "The tumor cell growth inhibitory effects of the BM analogs in human cancer cells with different levels of NQO1 were studied to determine if the size and position of the functional groups could determine the level of NQO1 required to activate the analogs." (PMID 21904446, 2009). "This approach could be used to develop new bioreductive antitumor agents for NQO1 targeted individualized cancer chemotherapy." (PMID 21904446, 2009). "This approach could be used to develop new bioreductive antitumor agents for NQO1 targeted individualized cancer chemotherapy that produce the optimal therapeutic index for each patient." (PMID 21904446, 2009). "Thus, the overexpression of HMOX1 and NQO1 observed in cancer cells treated with Ocoxin could have accounted for the subsequent mortality of those cells when exposed to the compound." (PMID 40176904, 2025). "Luteolin significantly inhibited Nrf2 and its target genes [NADPH quinone oxidoreductase 1 (NQO1), heme oxygenase-1 (HO-1), and GSTα1/2] in resistant cells, while the combination of luteolin with different chemotherapeutics demonstrated synergistic effects in anti-cancer activities." (PMID 39061884, 2024). "Furthermore, NQO1 was a protective antioxidant agent and a versatile cytoprotective agent that regulates oxidative stresses of chromatin-binding proteins, thereby mitigating DNA damage in cancer cells." (PMID 39505867, 2024).
cancer (continued). "Moreover, investigations on various human cancer cells revealed that NQO1 directly interferes with the unstructured DNA-binding domain of c-Fos and leads to the upregulation of cyclin-dependent kinase subunit-1 and the modulation of the cell-cycle progression at the G2/M phase." (PMID 38167027, 2024). "Consequently, NQO1 is identified as a potential target for cancer therapy." (PMID 38136388, 2023). "Therefore, more experimental work is needed to identify NQO1 function in cancer in further study." (PMID 37583897, 2023). "Thus, the increased expression of NQO1 could be a defensive, but inefficient, response of cancer cells to these treatments." (PMID 37175546, 2023). "Moreover, targeting PARP and NQO1 while inducing ferroptosis could simultaneously kill subpopulations of cancer cells with high and low NQO1 expression." (PMID 37169843, 2023). "Thus, the use of glutaminase inhibitors such as CB-839 could be a useful therapeutic strategy in cancer cells with high NQO1 expression since they can reduce glutamate availability, creating a metabolic bottleneck." (PMID 37175546, 2023). "The studies found and identified Nrf2 as a major regulator of chemoresistance in cancer stem cell (CSC)-enriched breast cancers as well as the activation of Nrf2-associated antioxidant genes such as HO-1, NQO1, Prx1, and others that leads to radioresistance in several other cancer cells." (PMID 35571115, 2022). "Whether NQO1 exclusively serves as a protective enzyme or plays a role in generating reactive metabolites, it should be investigated through toxicity, mutagenicity for cancer development." (PMID 36338728, 2022). "Furthermore, NQO1 plays a role in neutralizing oxidative stress and detoxification, which may promote cancer cell survival." (PMID 36142607, 2022). "Many previous reports have suggested that the activation of NRF2 in tumor cells could affect proliferation and accelerate the development of the disease, whose target gene NQO1 also plays an important role in cellular proliferation and is overexpressed in many cancer tissues." (PMID 35805773, 2022). "Furthermore, Nrf2-induced over expression of NQO1 can play a significant role in chemotherapy failures, where it may be an adaptive response to oxidative stress and cytotoxicity and provide cancer cells with defense." (PMID 34833955, 2021). "Although more in vivo studies are needed to elucidate therapeutic effects and the exact mechanism, our data identified targeting the enzymes in DNA repair pathways for therapeutic treatment may, have the potential to synergize with β-lap for treating human NQO1+ cancer." (PMID 34789190, 2021). "In NQO1-overexpressing cancer cells, ROS production in response to β-lapachone causes DNA damage and thereby triggers PARP-mediated NAD degradation to such an extent that it outweighs the possible increase in NAD caused by NQO1, ultimately causing cancer cell demise via NAD and ATP shortage." (PMID 34068917, 2021). "Hence NQO1 acts as both a cancer suppressor and tumor promoter." (PMID 34833955, 2021). "Also WA regulates the activity of antioxidant enzymes (such as superoxide dismutase) and mRNA expression of antioxidant genes: erythroid 2-like 2 (NFE2L2), heme oxygenase 1 (HMOX1), glutathione-disulfide reductase (GSR), and NAD(P)H quinone dehydrogenase 1 (NQO1)) in cancer cells." (PMID 33498013, 2021). "Indeed, the addition of an NQO1-inhibitor (e.g., dicoumarol) in cancers could sensitize the anti-cancer effects of certain agents by inhibiting resistance due to drug efflux." (PMID 32295316, 2020). "Therefore, although high levels of NQO1 could be exploited with a therapeutic intent in NRF2/KEAP1 mutant cancer cells, it is unclear whether actions of NRF2 could limit β-lapachone efficacy." (PMID 32007910, 2020). "Therefore, Nrf2 modulation and NQO1 stimulation could be important therapeutic targets for cancer prevention and treatment." (PMID 32645959, 2020).
cancer (continued). "The enzymes NQO1 and b5R might be good therapeutic targets for cancer and age-related diseases." (PMID 32645959, 2020). "However, there are many conflicting reports regarding the role of NQO1 in cancer development." (PMID 31886179, 2019). "Data show that in some cancer cells RH1 may act in an NQO1-independent way." (PMID 31336714, 2019). "NQO1 could serve as a target for cancer therapy through two different mechanisms: its inhibition can lead to cell growth suppression since the normal function of this enzyme in the cell is to protect them from mutagenic, carcinogenic and cytotoxic effects derived from quinones." (PMID 31388334, 2019). "Interestingly, NQO1 activity is increased in some forms of cancer." (PMID 30518535, 2019). "However, the data presented here demonstrate that the cancer-associated polymorphisms in NQO1 do not affect the enzyme’s ability to exhibit negative cooperativity towards the inhibitor dicoumarol." (PMID 31431515, 2019). "Indeed, several lines of evidence identified that increased NQO1 expression in cancer stem cells may increase stem-cell proliferation and survival by removing excess hydrogen peroxide." (PMID 30513573, 2018). "Consequently, identification of high affinity and selective inhibitors of NQO1 might be an attractive strategy for treating cancers." (PMID 30595797, 2018). "Moreover, inducers of NQO1 in vitro in the Hepa-1c1c7 model were also able to suppress the carcinogenic effects of diverse cancer promoting agents related to different types of cancers, with sulforaphane being the prototype NQO1 inducer." (PMID 29788962, 2018). "However, normal cells have lower NQO1 levels and are more insensitive to β-Lap than cancer cells." (PMID 28592850, 2017). "Taken together the status of NQO1 expression and activity is essential for the success of quinone-based chemotherapies, and therefore detailed biochemical and structural studies are paramount to generate a sound basis for the development and design of cancer intervention strategies." (PMID 28236663, 2017). "However, the ability of the isothiocyanate SFN to induce NQO1 functionality in NQO1*2 cancer cells remains largely unknown." (PMID 27625902, 2015). "Indeed, addition of BPTES to NQO1-overexpressing cancer cells decreased NADPH and GSH anti-oxidant defenses, which would otherwise counteract the ß-lap-induced ROS burst and thus lead to enhanced DNA damage, PARP-driven NAD+ and ATP depletion, and metabolic catastrophe." (PMID 26462257, 2015). "Additionally, NQO1 also shows superoxide scavenging activity as well as protective activity against procarcinogenic benzenes, thus it has been considered as an important defense of host against cancer." (PMID 25602258, 2015). "However, studies on NQO1 expression in cancer have been contradictory." (PMID 28983331, 2015). "Thus, the depletion of NQO1 prevents AMPK-induced cancer cell death in OGD." (PMID 25586669, 2015). "In addition, the high level of NQO1 expression in various tumors in combination with its ability to reduce many quinine-containing antitumor drugs has drawn attention to NQO1 as a potential molecular target in cancer treatment." (PMID 28983331, 2015). "Notably, NQO1 is also upregulated in various mammalian cancers." (PMID 24499631, 2014). "In addition, higher NQO1 expression or activity in cancer cells may make them more sensitive to β-lapachone." (PMID 24505400, 2014). "However, conclusions on the biological functions of NQO1 in cancer have been contradictory." (PMID 24912939, 2014). "In addition, the high level of NQO1 expression in solid tumors in combination with the ability to reduce many quinine-containing antitumor drugs has dawn attention to NQO1 as a potential molecular target in cancer treatment." (PMID 24499631, 2014). "Therefore, NQO1 is considered an important defense against cancer." (PMID 22272361, 2012). "Therefore, β-lap can selectively kill these human cancer cells that overexpress endogenous NQO1." (PMID 21738692, 2011).